RN7SKP103 (RN7SK pseudogene 103)
Gene: Miscellaneous RNA gene on chromosome 2 (132,523,617 to 132,523,936, forward strand). Ensembl gene ENSG00000200718.
Homologues: Orthologues: chimpanzee 7SK (99% identical), guinea pig 7SK (62% identical), mouse Gm54681 (59% identical), guinea pig 7SK (55% identical). Paralogues in human: RN7SKP79 (73% identical), 7SK (72% identical), RN7SKP180 (72% identical), RN7SKP217 (72% identical), RN7SKP3 (72% identical), RN7SKP9 (72% identical), RN7SKP162 (71% identical), RN7SKP176 (71% identical), RN7SKP20 (71% identical), RN7SKP25 (71% identical), RN7SKP36 (71% identical), RN7SKP95 (71% identical), and 283 more.